DUSP4 (dual specificity phosphatase 4)
Diseases named in the same sentence as DUSP4 in open-access papers (continued):
Sharing a sentence is not in itself a finding about the gene and the disease.
colorectal cancer (continued). "Studies pointed out that higher expression of DUSP4 could be discovered in more aggressive cancers, meanwhile the lower expression or knockout of DUSP4 would promote tumor development and progression in colorectal cancer and glioblastoma." (PMID 37153782, 2023). "Finally, in colorectal cancer models, silencing of DUSP4 enhanced cell proliferation and invasiveness, most reminiscent of the effect we observed in HCC cell lines." (PMID 37946160, 2023). "Studies have documented that low DUSP4 expression levels are found in more aggressive cancers while the knockdown of DUSP4 promotes tumor development and progression in colorectal cancer and glioblastoma, suggesting the role of DUSP4 as a tumor suppressor 24-25." (PMID 35864956, 2022). "In summary, we demonstrated that high DUSP4 expression could be detected in colorectal cancer tissues and cells." (PMID 32897241, 2020). "We also demonstrated the detailed molecular mechanisms of DUSP4 molecular in colorectal cancer." (PMID 32897241, 2020). "In addition, DUSP4 was closely related to the regulation of colorectal cancer cell migration and invasion." (PMID 32897241, 2020). "Therefore, the detailed molecular mechanisms of DUSP4 in the occurrence and development of colorectal cancer will provide important clinical references for the early diagnosis and prognosis evaluation of colorectal cancer." (PMID 32897241, 2020). "DUSP4 could aggravate cell proliferation, invasion, and migration in colorectal cancer by regulating Smad4 ubiquitylation degradation." (PMID 32897241, 2020). "The results indicated that DUSP4 could regulate the metastasis and proliferation of colorectal cancer cells in vitro." (PMID 32897241, 2020). "The aim of this study was to test the biological role of DUSP4 in colorectal cancer cells." (PMID 32897241, 2020). "DUSP4 overexpression increased proliferation in colorectal carcinoma cell lines." (PMID 29100381, 2017). "They concluded that DUSP4 expression was negatively correlated with factors reflecting tumor progression, including distant metastases in colorectal cancer, and suggested that DUSP4 may act as a tumor suppressor in colorectal cancer." (PMID 25688264, 2015). "Moreover, in colorectal cancer cells, DUSP4 could promote the Smad4 degradation by regulating ubiquitin-related Smad4 degradation, and promote the cell proliferation, migration and invasion by regulating Smad4 degradation via Smad4 gene." (PMID 32897241, 2020). "Downregulation of DUSP4 was noted in the deep region rather than in the superficial region in colorectal cancer." (PMID 34679636, 2021). "Our results revealed that DUSP4 and Smad4 could regulate EMT of colorectal cancer through E-caderin, N-caderin, Vitmentin, and MMP9 gene." (PMID 32897241, 2020). "We assessed the response to DUSP4 depletion in two BRAF-mutant nonmelanoma cell lines (the glioma line DBTRG and the colorectal carcinoma cell line, LS411N) that were sensitive to MAPK inhibitors." (PMID 35580987, 2022).
melanoma (19 papers, 2010 to 2025). A malignant, usually aggressive tumor composed of atypical, neoplastic melanocytes. "Our research reveals the molecular mechanism that links the hyperactivation of ERK signaling and loss of fitness after DUSP4 depletion in mutant melanoma cells." (PMID 35580987, 2022). "In the presence of drug, BRAF-mutant melanoma cells appear to suppress DUSP4 expression to compensate for the acute loss of oncogenic signals." (PMID 35580987, 2022). "Our results support the notion that further activation of MAPK signaling through loss of inhibitors such as DUSP4 in melanoma cells that already harbor activating BRAF or NRAS mutations is detrimental, a hypothesis that will need to be explored with further experiments." (PMID 32767816, 2021). "Thus, while previous studies showed a correlation between DUSP4 expression and MEK inhibitor sensitivity in pan-tumour cell line panels, we report for the first time that this association exists in clinical melanomas, and depleting DUSP4 expression induces resistance to MEK inhibition." (PMID 31839677, 2020). "Using high-MITF (SKMEL28) or low-MITF (A375) drug-naive BRAFV600E melanoma cell lines, we derived MAPKi-resistant cell models to evaluate the role of DUSP4 in this setting." (PMID 35580987, 2022). "Taken together, these results indicate that DUSP4 selectively controls cell viability in BRAF-mutant melanoma cells by functioning as a rheostat for ERK signaling which in turn drives the PAX3-MITF pathway." (PMID 35580987, 2022). "Subsequent investigation in BRAF WT melanoma cell lines indicated that DUSP4 depletion enhanced cell survival and decreased sensitivity to MEK inhibition." (PMID 36576731, 2022). "Overall, our data show that MAPK overdose driven by DUSP4 inactivation can effectively and selectively kill mutant melanoma cells with melanocytic identity." (PMID 35580987, 2022). "Our study demonstrates that in BRAF- and NRAS-mutant MITF-proficient melanoma, the DUSP4 MAPK phosphatase restricts MAPK activation and prevents oncogenic overdose through modulation of MITF function." (PMID 35580987, 2022). "We found that depletion of the ERK phosphatase DUSP4 induces oncogene overdose and loss of fitness in both drug-naive and drug-resistant BRAF-mutant melanoma cell lines." (PMID 35580987, 2022). "Our data show that both MITF-high and MITF-low BRAF-mutant melanoma cells can acquire MAPKi resistance and that their response to DUSP4 depletion remains unchanged despite changes in MITF levels during the acquisition of drug resistance." (PMID 35580987, 2022). "Overall, these results indicate that MAPK pathway de-inhibition through DUSP4 inactivation can potently impair the growth of BRAF-mutant melanoma cells." (PMID 35580987, 2022). "We extended these observations by analyzing the effects of DUSP4 knockdown in two additional BRAFV600E melanoma cell lines and found similar results." (PMID 35580987, 2022). "DUSP6 is an oncogenic factor in melanoma, and DUSP4 can play its part in the survival and growth of melanoma cells by inhibiting the DUSP6 expression." (PMID 36059641, 2022). "To assess the impact of DUSP4 depletion on the activation of various MAPKs in cells, we measured the phosphorylated form of ERK and the two stress-activated MAPKs JNK and p38, after DUSP4 down-regulation in BRAF-mutant melanoma cells." (PMID 35580987, 2022). "The heterogeneity of MITF levels in melanoma restricts the essential role of DUSP4 to high- and moderate-MITF–expressing cells." (PMID 35580987, 2022). "We found that DUSP4 knockdown in four different BRAF-mutant melanoma cell lines induced significant proliferation arrest and apoptotic cell death as judged by dye dilution and Annexin V staining, respectively." (PMID 35580987, 2022). "In vitro experiments in human melanoma cell lines confirmed that inactivation of DUSP4 and PPP2R2A results in decreased cell proliferation." (PMID 32767816, 2021).
melanoma (continued). "DUSP4 encodes an inhibitor of ERK, suggesting that further activation of MAPK signaling activity through its loss is selectively deleterious to melanoma cells." (PMID 32767816, 2021). "Next, we examined the effects of DUSP4 and PPP2R2A depletion in two additional melanoma cell lines, both harboring BRAF mutations." (PMID 32767816, 2021). "We report here that two components of the MEK 6 gene score, ETV4 and DUSP4, were expressed at significantly higher levels in melanomas of responders to docetaxel plus selumetinib compared with those who progressed at first assessment." (PMID 31839677, 2020). "DUSP4 was the only other component of the MEK 6 gene score that was expressed at significantly higher levels in the melanomas of patients who responded to selumetinib and docetaxel, compared with those who progressed at first assessment." (PMID 31839677, 2020). "Overall, Usp9x appears to control ubiquitination of proteins essential in melanoma 3D growth (Ets-1) and attenuation of kinase signalling (Dusp4)." (PMID 28198367, 2017). "Notably, in all human melanoma studies reported in cBioPortal, there is a significant positive correlation between DUSP4 and MITF mRNA expression." (PMID 35580987, 2022). "Thus, independently of the activating lesion, melanoma cells with mutationally active MAPK and a functional MITF pathway are vulnerable to DUSP4 depletion." (PMID 35580987, 2022). "MITF has been previously implicated in melanoma survival pathways, suggesting that the suppression of MITF gene expression could explain the defective cell growth observed in DUSP4 knockdown cells." (PMID 35580987, 2022). "The data also suggest that DUSP4 may be critical in maintaining the appropriate level of ERK activity in BRAF-mutant melanoma cells." (PMID 35580987, 2022). "Moreover, we demonstrate that drug-naive NRAS-mutant melanoma cells are also sensitive to DUSP4 silencing, thus broadening the therapeutic potential of targeting this phosphatase." (PMID 35580987, 2022). "Genetic inactivation of DUSP4 significantly reduced proliferation in a melanoma cell line that was included in the CRISPR‐Cas9 screens performed by the Broad institute (WM983B) as well as an independent melanoma cell line (A375)." (PMID 32767816, 2021). "In melanomas of patients on the selumetinib but not the placebo arm, two gene signature components, dual-specificity protein phosphatase 4 (DUSP4) and ETS translocation variant 4 (ETV4), were expressed more highly in responders than non-responders." (PMID 31839677, 2020). "We wished to extend this observation by ascertaining whether DUSP4 or ETV4 might also influence the response of wild-type BRAF melanoma cells to MEK inhibition." (PMID 31839677, 2020). "Interestingly, DUSP4 silencing led to the selective accumulation of the phospho-form of ERK in the two cell lines analyzed, suggesting that in melanoma cells, DUSP4 activity may be primarily directed toward ERK." (PMID 35580987, 2022). "However, other Usp9x substrates may also add (for example, Mcl-1) or diminish (for example, Dusp4) anti-tumour activity of Usp9x inhibition and will need to be further examined in melanoma and other tumours." (PMID 28198367, 2017). "The depletion of DUSP4 induce oncogene overdose in both drug-naïve and drug-resistant BRAF-mutant melanoma cell lines through the hyperactivation of MAPK signaling." (PMID 40141318, 2025). "DUSP4, a negative regulator of ERK activity, was found to be expressed at elevated levels in MAPK mutant melanomas." (PMID 37803324, 2023). "As our data show that DUSP4 depletion leads to cell death through MITF suppression, we evaluated the sensitivity of BRAF/NRAS–mutant melanoma cells expressing either high or low levels of MITF to DUSP4 knockdown." (PMID 35580987, 2022).
melanoma (continued). "We further validated the results from our screen by individually silencing the expression of DUSP4 and two other DUSP family members with roughly similar substrate selectivity (DUSP6 and DUSP10) in two different BRAFV600E melanoma cell lines." (PMID 35580987, 2022). "Here, we demonstrate that depletion of the ERK phosphatase, DUSP4, leads to toxic levels of MAPK activation in both drug-naive and drug-resistant mutant melanoma cells." (PMID 35580987, 2022). "Among all genes analyzed, DUSP4 appeared to have a major role in controlling the viability of BRAF- and NRAS-mutant melanoma cells." (PMID 35580987, 2022). "Decreased protein levels of DUSP4 and PPP2RA were detected in all melanoma cell lines by immunoblot analysis up to 10 days after transduction confirming the effects of DUSP4 and PPP2RA on cellular fitness in melanoma cell lines." (PMID 32767816, 2021). "We verified that genetic inactivation of DUSP4 and PPP2R2A reduces the proliferation of melanoma cells." (PMID 32767816, 2021). "We investigate a possible role for DUSP4 and ETV4 in mediating this response by assessing the effect of their depletion on the sensitivity of BRAF wild-type melanoma cells to MEK inhibition." (PMID 31839677, 2020). "It has been reported that BOP1 knockdown resulted in the downregulation of the MAPK phosphatases DUSP4 and DUSP6 and further increased MAPK signaling and resistance to BRAF kinase inhibitors in melanoma." (PMID 32167616, 2020). "A potential mechanism of ERBB activation in Class II melanomas is minimal expression of the ERK1/2 phosphatase, DUSP4, as ectopic restoration of DUSP4 attenuated ERBB signaling through potential modulation of the ERBB ligand, amphiregulin (AREG)." (PMID 26084293, 2015). "At the level of protein, NHEM displayed almost no expression of most of the proteins, whereas in the majority of examined melanoma cell lines FOSL1, IGFBP3 and DUSP4 were strongly expressed." (PMID 20663135, 2010). "In particular, we found that the absence of DUSP4 in melanoma cells leads to excessive levels of active ERK." (PMID 35580987, 2022). "This correlation from a large human melanoma dataset supports our hypothesis that MITF and DUSP4 are functionally co-dependent." (PMID 35580987, 2022). "DUSP4 depletion was recently reported to diminish the negative effects on melanoma cell viability induced by MEK inhibitors through increasing MAPK activity." (PMID 32767816, 2021). "We verified the fitness effects of DUSP4 and PPP2R2A in multiple melanoma cell lines." (PMID 32767816, 2021). "Targeting negative regulators of MAPK signaling inhibitors such as DUSP4 and PEA15 further activates MAPK signaling and may therefore be particularly effective in eliminating melanoma cells that have acquired resistance to BRAF and MEK inhibition." (PMID 32767816, 2021). "We hypothesize that once melanoma cells have acquired resistance to treatment with BRAF and MEK inhibitors by upregulation of MAPK activity they will become more sensitive to DUSP4 inhibition." (PMID 32767816, 2021). "RNA sequencing analysis of DUSP4, EGFR, HER2 and HER3 expression in pan-negative melanomas genotyped through The Cancer Genome Atlas (TCGA) revealed an inverse relationship between DUSP4 and EGFR expression (p-value = 0.03978)." (PMID 26084293, 2015). "Immunohistochemical analysis of BRAF-mutant, NRAS-mutant and pan-negative patient melanomas revealed wide heterogeneity of DUSP4 expression in each subtype." (PMID 26084293, 2015). "We also reveal that a potential mechanism of heightened ERBB activity in Class II pan-negative melanomas is the relative lack of DUSP4 expression, a negative regulator of ERK1/2." (PMID 26084293, 2015). "In summary, we have identified a subset of pan-negative melanoma with reduced sensitivity to MEK1/2 inhibition that is mediated by an axis involving ERBB activation/DUSP4 expression." (PMID 26084293, 2015).
melanoma (continued). "They include the prostate cancer suppressor NXK3-1, the gene CSMD1, which is recurrently deleted in melanoma, and the phosphatase DUSP4, which is involved in negative feedback control of EGFR signaling in lung adenocarcinoma." (PMID 25160065, 2014). "Importantly, we found that FOSL1, OPN, IGFBP3, DUSP4, and TAAL6 also exhibited increased expression levels in human melanoma cell lines compared to human melanocytes." (PMID 20663135, 2010). "Notably, the inactivation of DUSP4 and PPP2R2A significantly reduced melanoma cell proliferation." (PMID 39200315, 2024). "Deletion of negative ERK regulators, including DUSP4, DUSP6, and PEA15, induced cell death in BRAF and NRAS mutant melanomas due to unrestrained activation of ERK." (PMID 37803324, 2023). "To determine whether this was the case in Class II pan-negative melanomas, we analyzed the six original Class I & II cells by immunoblot analysis and observed DUSP4 expression existed primarily in Class I cells, whereas Class II cells harbored little to no DUSP4 expression." (PMID 26084293, 2015). "Realtime PCR revealed a significantly higher expression of FOSL1, OPN, IGFBP3, DUSP4 and TAAL6 in most of the melanoma cell lines compared to normal melanocytes." (PMID 20663135, 2010). "Here, we investigated sensitivity to MEK1/2 inhibition in 16 pan-negative melanoma cell lines and found that differences in ERBB activation and DUSP4 expression may modulate responses." (PMID 26084293, 2015). "DUSP4 and PPP2R2A were homogenously expressed among the 28 melanoma cell lines and transcript levels did not provide an explanation for the difference in sensitivity to inactivation—this might imply post‐translational factor influence on the function of these genes." (PMID 32767816, 2021).
gastric cancer (13 papers, 2017 to 2023). A primary or metastatic malignant neoplasm involving the stomach. "In the present study, we aimed to explore the role of DUSP4 in DOX resistance in GC cell lines, uncover the associated mechanisms, and investigate the link between the EMT and doxorubicin resistance in gastric cancer." (PMID 29212207, 2017). "In contrast, studies in breast and gastric cancer demonstrated that siRNA-mediated depletion of DUSP4 resulted in sensitization of cell lines to doxorubicin." (PMID 36576731, 2022). "Overexpression of DUSP4 effectively suppressed the proliferation of gastric cancer cells and induced apoptosis." (PMID 35069911, 2022). "For instance, miR-122-5p impeded cell migration and invasion by negatively modulating DUSP4 in gastric cancer." (PMID 32905397, 2020). "This study aimed to investigate the mechanism of DUSP4 regulating doxorubicin resistance in gastric cancer cells." (PMID 29212207, 2017). "MiR‐122‐5p inhibited the migration and invasion of gastric cancer cells by inhibiting DUSP4." (PMID 31373443, 2019). "Overexpression of DUSP4 was more resistant to doxorubicin in gastric cancer cells." (PMID 29212207, 2017). "Knockdown of DUSP4 increased the sensitivity of gastric cancer cells to doxorubicin." (PMID 29212207, 2017). "Moreover, up-regulation of DUSP4 promoted the Epithelial-Mesenchymal Transition (EMT) in gastric cancer cells, but blocking the EMT using a Twist siRNA increased the sensitivity of gastric cancer cells to doxorubicin and confirmed the EMT was involved in DUSP4-mediated doxorubicin resistance." (PMID 29212207, 2017). "DUSP4 is a promoter of EMT, and targeting DUSP4 can alleviate the EMT process and suppress tumor growth and drug resistance in breast and gastric cancer." (PMID 36127345, 2022).